UCHL1 (ubiquitin C-terminal hydrolase L1)
Diseases named in the same sentence as UCHL1 in open-access papers (continued):
Sharing a sentence is not in itself a finding about the gene and the disease.
renal cell carcinoma (5 papers, 2009 to 2026). "Aberrant expression of UCHL1 has been found in a number of human solid tumors including renal cell carcinoma (RCC)." (PMID 19857250, 2009). "Several studies demonstrated aberrant UCHL1 expression in acute lymphoblastic leukaemia, myeloma, melanoma, neuroblastoma, pancreatic, esophageal, lung, thyroid, colon and renal cell carcinoma (RCC)." (PMID 19857250, 2009). "Targeting AR and UCHL1 may serve as a novel target for Xp11.2 translocation renal cell carcinoma therapy." (PMID 35452181, 2022). "In addition, UCHL1 expression was detected during kidney development, in particular during the differentiation of renal tubules representing the origin of clear cell renal cell carcinoma (RCC) and in the regulation of the cell cycle of parietal epithelial cells of the Bowman's capsule." (PMID 19857250, 2009).
squamous cell carcinoma (5 papers, 2006 to 2022). A carcinoma arising from squamous epithelial cells. "With regards to routine histopathological workup, we identified KRT18 in combination with UCHL1 as potential immunohistochemical markers to differentiate NEC-like IDH2 and NEC-like SMARCA4/ARID1A tumors from adenoid cystic carcinomas, olfactory neuroblastomas and squamous cell carcinomas." (PMID 36443295, 2022). "UCHL1 expression was high in NEC-like IDH2 and NEC-like SMARCA4/ARID1A tumors as well as olfactory neuroblastomas but absent in tumors from the ACC class and squamous cell carcinomas." (PMID 36443295, 2022).
type 2 diabetes (5 papers, 2015 to 2025). "UCHL1 relieves the apoptotic burden induced by the accumulation of intracellular toxic oligomers of islet amyloid polypeptide (IAPP) in pancreatic beta (β) cells, resulting in the suppression of type 2 diabetes." (PMID 33919439, 2021).
B-cell lymphoma (4 papers, 2015 to 2019). "The data presented here reveal that AIP is a positive regulator of BCL6 protein expression, which is commonly upregulated in B cell lymphomas, and show that AIP binds to an E3 ligase (FBXO11) and a DUB (UCHL1), both of which have been associated with DLBCL pathobiology." (PMID 31042473, 2019).
cryptorchidism (4 papers, 2017 to 2023). The failure of one or both testes of a male fetus to descend from the abdomen into the scrotum during the late part of pregnancy. "Despite this, it should be mentioned that our earlier research on UCHL1 as a potential marker showed a higher concentration of this deubiquitinating enzyme in the case of cryptorchidism, thermal injury, and acute appendicitis." (PMID 36854961, 2023). "Our previous studies show that in children, UCHL-1 is overexpressed in cases of cryptorchidism, acute appendicitis and thermal injury." (PMID 32987792, 2020). "To confirm findings from animal models, we wanted to evaluate the concentration of UCHL1 in the blood plasma of boys with cryptorchidism and if there is any correlation with patient age." (PMID 29401475, 2018). "The median concentration of UCHL1 in the blood plasma of boys with cryptorchidism, was 5-folds higher than in boys with inguinal hernia, whose testicles were located in the scrotum." (PMID 29401475, 2018). "To investigate the ubiquitin carboxyl-terminal hydrolase 1 (UCHL1) in blood plasma of boys with cryptorchidism, we used a novel technique Surface PLASMON RESONANCE Imaging (SPRI)." (PMID 29401475, 2018). "To investigate UCHL1 in blood plasma of boys with cryptorchidism, we used a novel technique Surface PLASMON RESONANCE Imaging (SPRI)." (PMID 29401475, 2018). "Purpose: to evaluate the concentration of ubiquitin carboxyl-terminal hydrolase 1 (UCHL1) in the blood plasma of boys with cryptorchidism and if there is any correlation with patient age." (PMID 29401475, 2018). "We believe, that the results of our study, indicate that Uchl1 concentrations in the blood plasma of boys with cryptorchidism, reflect the heat-induced apoptosis of germ cells." (PMID 29401475, 2018). "The levels of UCHL1 in the blood plasma of our patients with cryptorchidism, were 5-folds higher than in controls, whose testicles were located in the scrotum." (PMID 29401475, 2018). "We also noticed statistically significant difference between UCHL1 levels in boys with cryptorchidism up to 2 years old, and above 2 years old." (PMID 29401475, 2018). "Furthermore, we also noticed that UCHL1 concentrations differed between the group of boys with cryptorchidism up to 2 years old, and above 2 years old." (PMID 29401475, 2018). "Uchl1 concentrations in the blood plasma of boys with cryptorchidism, may reflect the heat-induced apoptosis of germ cells." (PMID 29401475, 2018). "We believe, that our study may help to understand its molecular consequences, influencing future fertility in patients with undescended testes.Uchl1 concentrations in the blood plasma of boys with cryptorchidism, may reflect the heat-induced apoptosis of germ cells." (PMID 29401475, 2018).
glomerulonephritis (4 papers, 2023 to 2025). A renal disorder characterized by damage in the glomeruli. "UCHL1 is regulated by NF-κB in podocytes in glomerulonephritis." (PMID 38175721, 2024). "In addition, UCHL1 modulates podocyte injury via destroying proteasomes in glomerulonephritis." (PMID 38175721, 2024).
Hypertension (4 papers, 2017 to 2025). The presence of chronic increased pressure in the systemic arterial system. "Moreover, the effect of Tianma on correcting the function and activity of Tpi1, Ppia, Ncam1, Uchl1, Septin-2 and Hsp90aa1 proteins, provided conclusive evidence for Tianma in the treatment of seizures, hypertension and headaches." (PMID 29262557, 2017). "Overall, our study identified UCHL1 as a novel regulator that contributes to Ang II-induced AF and suggests that the administration of LDN may represent a potential therapeutic approach for treating hypertensive AF." (PMID 31700166, 2020).
Lysosomal storage disorders (4 papers, 2008 to 2020). "In fact, such a model has been used and accepted previously in studies on expression of behavior-related gene, UCHL1, in several lysosomal storage diseases." (PMID 32050523, 2020). "Although we detected highly increased levels of UCHL1 mRNA in MPS IIIB fibroblasts, another report demonstrated previously decreased levels of the gene product in several lysosomal storage diseases, including sialidosis, galactosialidosis, GM1-gangliosidosis, MPS IVA, MPS IVB, and Gaucher disease." (PMID 32050523, 2020). "Lysosomal storage disorders and lysosomal cysteine protease inhibitor E64 treatment were previously shown to down-regulate UCHL1, however, such is not the case in Ctsd-/- brains in our study, indicating a distinct mechanism of CD deficiency-induced proteasome dysfunction." (PMID 19021916, 2008).
medullary thyroid carcinoma (4 papers, 2022 to 2025). "In medullary thyroid carcinoma, inhibition of ZFAS1 also inhibited tumor growth and metastasis through the miR-214-3p/UCHL1/EPAS1 pathway, providing evidence of its role in cancer aggressiveness." (PMID 41154428, 2025).
metastatic carcinoma (4 papers, 2018 to 2024). A carcinoma which has spread from the original site of growth to another anatomic site. "UCHL1 overexpression in CCRCC was associated with a more aggressive potential and metastatic cancer phenotype and, in some cases, a poor prognosis for the patient." (PMID 39199615, 2024).
myocardial infarction (4 papers, 2020 to 2025). Gross necrosis of the myocardium, as a result of interruption of the blood supply to the area, as in coronary thrombosis. "Besides, an article on ischemic heart injury reported that UCHL1 might play a novel protective role on myocardial infarction via stabilizing hypoxia-inducible factor 1 alpha and promoting its signaling." (PMID 41036271, 2025).
proteinopathy (4 papers, 2014 to 2025). "The UCHL1 protein has been implicated in protein misfolding diseases." (PMID 24450868, 2014). "UCHL1 is abundantly expressed in corticospinal motor neurons (CSMN) that become affected in TDP-43 proteinopathies which made its promoter ideal for our study." (PMID 32979923, 2020). "Two protein components of the ubiquitin-proteasomal system (UPS)—ubiquitin-C-terminal hydrolase (UCHL1), a deubiquitinase, and polyubiquitin-B (UBB) —accumulate in post-MI aggregates, contributing to dysfunctional synaptic activity and proteinopathy that arises after cardiovascular disease." (PMID 40332607, 2025).
viral infection (4 papers, 2014 to 2021). "Serum UCHL1 has been a biomarker for brain damage in various studies including those complicated with virus infection." (PMID 34504487, 2021). "The deubiquitinases OTUB1/2, UCHL1, MYSM1 and DUBA inhibit K63-linked ubiquitination of TRAF3 or TRAF6 and negatively regulate IFNs production during viral infection." (PMID 29734366, 2018). "Similarly, it has been reported that some deubiquitinases including OTUB1/2, UCHL1, MYSM1 and DUBA can remove K63-linked ubiquitination of either TRAF3 or TRAF6, thus inhibiting IFNs production during viral infection." (PMID 29734366, 2018). "So far, several deubiquitinases such as DUBA, OTUB1/2, UCHL1, and OTUD7B have been reported to cleave TRAF3 ubiquitin chains in response to viral infection." (PMID 24763515, 2014). "We first screened the reported deubiquitinases for TRAF3 and found that HSCARG interacted with OTUB1 more potently than OTUB2, UCHL1, OTUD7B, and USP25, and this interaction was enhanced by viral infection." (PMID 24763515, 2014).
adenoma (3 papers, 2021 to 2023). A neoplasm arising from the epithelium. "In addition to WT1, we also found carcinoma-specific upregulation of LGALS3 (galectin-3) and UCHL1 (PGP9.5) (also upregulated in adenoma), which has been suggested as an IHC marker in parathyroid carcinoma." (PMID 37121965, 2023).
astrocytomas (3 papers, 2015 to 2023). "Fold change in expression of UCHL1 gene relative to the reference gene 18S in the control group and different grade astrocytomas." (PMID 37390278, 2023). "Using a lentiviral knockdown system, we investigated the effect of UCHL1 inhibition on astrocytoma cell invasion, cell proliferation, and on the stem-like cancer cell population." (PMID 28472177, 2017). "Future work will explore the biological relevance of the differences in UCHL1 expression among the various WHO grade astrocytomas." (PMID 28472177, 2017).
atrial fibrillation (3 papers, 2020 to 2022). A disorder characterized by an electrocardiographic finding of a supraventricular arrhythmia characterized by the replacement of consistent P waves by rapid oscillations or fibrillatory waves that vary in size, shape and timing and are accompanied by an irregular ventricular response. "The inhibition of UCHL1 by LDN (a specific inhibitor) significantly reduced the Ang II-induced increase in blood pressure, atrial fibrillation, fibrosis, inflammation, and oxidative stress." (PMID 31700166, 2020).
cerebral malaria (3 papers, 2023 to 2024). A sequestration of Plasmodium falciparum in the brain, which can cause coma and/or seizures. "In cerebral malaria, both markers are associated with worse cognition, while in severe malarial anaemia, only ubiquitin C-terminal hydrolase-L1 is associated with worse cognition." (PMID 38075948, 2023). "In cerebral malaria, elevated neurofilament-light chain is associated with mortality whereas elevated ubiquitin C-terminal hydrolase-L1 is associated with blood–brain barrier dysfunction and neurodeficits over follow-up." (PMID 38075948, 2023). "We aimed to investigate whether a multi-analyte panel including ubiquitin C-terminal hydrolase-L1, neurofilament-light chain, and glial fibrillary acidic protein can serve as biomarkers of brain injury associated with mortality and neurodisability in cerebral malaria and severe malarial anaemia." (PMID 38075948, 2023). "Ubiquitin C-terminal hydrolase-L1 and neurofilament-light chain levels are elevated in paediatric cerebral malaria and severe malarial anaemia." (PMID 38075948, 2023). "Admission ubiquitin C-terminal hydrolase-L1 levels were elevated >95th percentile of community children in 71 and 51%, and neurofilament-light chain levels were elevated >95th percentile of community children in 40 and 37% of children with cerebral malaria and severe malarial anaemia, respectively." (PMID 38075948, 2023).
colitis (3 papers, 2020 to 2023). Inflammation of the colon. "Here, we demonstrated an attenuated expression of UCHL-1 in rat colitis induced by TNBS, which is consistent with our previous findings." (PMID 34884536, 2021).
endometrial cancer (3 papers, 2020 to 2022). Primary or metastatic malignant neoplasm involving the endometrium (mucous membrane that lines the endometrial cavity). "As overexpression of cyclin B1 has been reported to contribute to development of aneuploidy, we also examined whether UCHL1 and cyclin B1 were associated with aneuploidy status in endometrial cancer." (PMID 31906456, 2020). "UCHL1 gene silencing limits the proliferation of endometrial cancer cells and delays the cell cycle." (PMID 35546675, 2022). "The product of the UCHL1 gene, ubiquitin C-terminal hydrolase L1, has been described as a key player in the metastases formation of tumors in most tumor types, thus also in endometrial carcinoma." (PMID 34503158, 2021). "By analyzing endometrial cancer samples from The Cancer Genome Atlas (TCGA), we found Ubiquitin Carboxyl-Terminal Hydrolase L1 (UCHL1) to be highly expressed in USC and to correlate with poorer overall survival." (PMID 31906456, 2020). "One study reported poor prognosis of high UCHL1 expression in endometrial cancer patients {Nakao, 2018 #10033}." (PMID 31906456, 2020). "Our data also shows that UCHL1 is only minimally expressed in normal endometrial tissue and low-grade EEC, but exhibits marked upregulation in high-grade EEC and USC, suggesting that its expression is an indicator of tumor aggressiveness in endometrial cancer." (PMID 31906456, 2020).
endometriosis (3 papers, 2015 to 2025). The growth of functional endometrial tissue in anatomic sites outside the uterine body. "It has been reported that UCHL1 dysfunction is associated with many neurodegenerative diseases, while there are few reports on UCH1 and endometriosis." (PMID 34917684, 2021).
hereditary spastic paraplegia (3 papers, 2020 to 2025). "Five missense mutations in human UCHL1 gene have so far been associated with autosomal dominant PD, recessive hereditary spastic paraplegia (SPG79) and early onset of progressive neurodegeneration." (PMID 33028204, 2020). "Furthermore, transcripts of disease-associated genes, such as BSCL2-206, REEP1-201, UCHL1-207/209 and KIF5A-202, all associated with hereditary spastic paraplegia (HSP), were significantly differentially expressed." (PMID 40735840, 2025). "Other forms of early-onset Hereditary Spastic Paraplegia may present with a similar clinical profile, such as SPG35 (FA2H), SPG79B (UCHL1), SPG11, and SPG15 (usually with even more complicated phenotypes)." (PMID 40757543, 2024).
Hypoglycemia (3 papers, 2021 to 2023). A decreased concentration of glucose in the blood. "Our results showed that significant changes in S100B, NSE, GFAP, UCHL-1, ACT concentrations, and CK-BB enzyme activity occurred in calves with diarrhea related to hypoglycemia, and hypoglycemia was associated with high mortality." (PMID 38026658, 2023). "None of S100B, NSE, GFAP, UCHL-1, ACT, AM, and CK-BB were found to be significant (p > 0.05) in predicting mortality in calves with hypoglycemia." (PMID 38026658, 2023).
leiomyoma (3 papers, 2022 to 2024). A well-circumscribed benign smooth muscle neoplasm characterized by the presence of spindle cells with cigar-shaped nuclei, interlacing fascicles, and a whorled pattern. "When compared to myometrial cells, UCHL1 mRNA and protein levels considerably increased in leiomyoma cells, and collagen levels decreased with the UCHL1-specific inhibitor LDN57444." (PMID 36830563, 2023). "To explore the effect of UCHL1 silencing and inhibition in leiomyoma and myometrial cells, we detected the expression of COL1A1 and COL3A1 mRNA using quantitative real-time PCR." (PMID 36830563, 2023). "In cultured leiomyoma and myometrial cells, UCHL1 is known to be upregulated at least two-fold compared to in these tissues." (PMID 36830563, 2023). "In the wound-healing assay, wound closure in the UCHL1 shRNA group significantly decreased in leiomyoma and myometrial cells by suppressing UCHL1 expression." (PMID 36830563, 2023). "To explore the effects of UCHL1 knockdown and inhibition in leiomyoma and myometrial cells, we determined the mRNA expressions of COL1A1 and COL3A1." (PMID 36830563, 2023). "COL1A1 and COL3A1 expression levels were downregulated after inhibition of UCHL1 in human leiomyoma cells." (PMID 36830563, 2023). "The immunohistochemical analyses revealed that UCHL1 was more positive in leiomyoma tissues when compared to myometrial tissues." (PMID 36830563, 2023). "Our study has shown that the level of UCHL1 in leiomyomas is higher than that in the matched myometrium." (PMID 36830563, 2023). "We found that the inhibition of UCHL1 reduced components of the extracellular matrix, including collagen 1A1 and 3A1, in leiomyoma cells." (PMID 36830563, 2023). "Leiomyoma cell migration, gel contraction, and collagen synthesis considerably improved after the administration of the UCHL1 inhibitor LDN57444." (PMID 36830563, 2023). "The collagen gel contraction assay was performed to determine collagen gel contractility in UCHL1 knockdown leiomyoma and myometrial cells." (PMID 36830563, 2023). "In this study, we investigated the mechanisms by which UCHL1 contributed to the pathology of uterine leiomyoma and showed a unique process of leiomyoma development by UCHL1." (PMID 36830563, 2023). "Quantitative real-time PCR results also confirmed that the UCHL1 mRNA expression level significantly increased in leiomyoma when compared to myometrial tissues." (PMID 36830563, 2023). "After incubation for 96 h, collagen gel contraction showed a significantly lower decrease in UCHL1 shRNA of leiomyoma cells than in the control group." (PMID 36830563, 2023). "In contrast to FH-deficient leiomyomas that also display NRF2 activation, but presumably functional neddylation, we identified the deubiquitin gene UCHL1 as one of the most uniquely upregulated genes in AKR1B10hi tumors." (PMID 36068196, 2022). "Here, we found that UCHL1 is aberrantly upregulated in leiomyomas." (PMID 36830563, 2023). "Our most intriguing observation may be the fact that a pharmacological inhibitor (LDN57444) with specificity for UCHL1 was able to decrease collagen formation in leiomyoma damage." (PMID 36830563, 2023). "In conclusion, these results indicate that UCHL1 is involved in the growth of leiomyoma in humans." (PMID 36830563, 2023). "Therefore, UCHL1 and myometrial hypoperfusion have been suggested to contribute to leiomyomas’ development." (PMID 36830563, 2023). "Furthermore, we analyzed protein expression by Western blotting and found that the protein expression level of UCHL1 significantly increased in leiomyoma." (PMID 36830563, 2023). "Furthermore, the elimination of UCHL1 significantly decreased the migration and contractility of leiomyoma cells." (PMID 36830563, 2023). "Furthermore, according to our results, leiomyoma cell activity significantly decreased with the UCHL1-specific inhibitor LDN57444." (PMID 36830563, 2023). "Furthermore, UCHL1 therapy reduced collagen gel contraction and wound healing in leiomyoma cells." (PMID 36830563, 2023).